CHEK1 (checkpoint kinase 1)
Diseases named in the same sentence as CHEK1 in open-access papers (continued):
Sharing a sentence is not in itself a finding about the gene and the disease.
nephronophthisis (1 paper, 2017). Progressive tubulointerstitial injury, inherited in an autosomal recessive pattern, caused by mutations in genes involved in ciliary function, which may result in an end stage renal failure.
neurofibroma (1 paper, 2023). An intraneural or extraneural neoplasm arising from nerve tissues and neural sheaths. "In addition to CHEK1, neurofibromas frequently harbor alterations in PRKDC, which may contribute to resistance." (PMID 38136356, 2023).
pleural mesothelioma (1 paper, 2016). A neoplasm that arises from the mesothelial cells of the pleura. "Further, CHEK1, required for checkpoint mediated cell cycle arrest in response to DNA damage, is overexpressed in pleural mesotheliomas." (PMID 28191281, 2016). "A CHEK1 inhibitor, LY2606369, is currently used in clinical trials for breast cancer patients with BRCA1/2 mutations and could be re-purposed for treating pleural mesothelioma malignancy." (PMID 28191281, 2016).
renal angiomyolipoma (1 paper, 2022). "Our small-molecule chemical screens reveal a sensitivity to inhibitors of checkpoint kinase 1/2 (CHK1/2), regulators of cell cycle, and DNA damage response, in both in vitro and in vivo models of TSC2-deficient renal angiomyolipoma (RA) tumors." (PMID 35359406, 2022).
cancer (779 papers, 2007 to 2026). A tumor composed of atypical neoplastic, often pleomorphic cells that invade other tissues. "Studies in oncology revealed that CHEK1 exhibits alterations in 0.80% of all cancers and mutations in 2.62% of malignant solid tumors." (PMID 40561071, 2025). "Several genes and gene products were identified as targets of miR-223, including NLRP3, IL18, IL1β, DNA methyltransferase 1, and checkpoint kinase-1, signifying its potential use as a cancer-specific diagnostic biomarker and therapy." (PMID 35205115, 2022). "As another important avenue of DNA damage response involved in cell cycle control, mutations in ATR and CHEK1 also have roles in the development of certain cancers." (PMID 36358700, 2022). "Most of the down-regulated hub proteins (ESR1, MCL1, LCK, TBP, and PCNA) play roles in the proliferation or survival of cancer cells, and CHEK1 is associated with the cell cycle checkpoint in cancer cells." (PMID 35563525, 2022). "The database was queried for CHEK1 gene mutations in 82,899 samples from 275 studies that covered the entire set of available cancers." (PMID 32178478, 2020). "It was reported that CHEK1 is altered in 0.80% of all cancers and mutated in 2.62% of malignant solid tumors." (PMID 32178478, 2020). "The exact underlying mechanism through which CHEK1 modulates cancer progression needs to be further investigated." (PMID 32178478, 2020). "Accumulating evidence demonstrates that ATR-checkpoint kinase 1 (Chk1) pathway can be considered as potential therapeutic strategies for ATM-deficient cancers." (PMID 30975222, 2019). "Cancers with mutations in tumor suppressor genes (TSG) that are synthetically lethal with therapeutic targets such as CHEK1 should be particularly sensitive to inhibition of that target." (PMID 26437225, 2015). "Given that dysregulation of the cell cycle is a hallmark of cancer, the pathway involving FBXO7, P27, and CHEK1 may represent an exploitable therapeutic target, particularly for cancers exhibiting FBXO7 copy number losses." (PMID 40896366, 2025). "Inhibition of CHEK2 by AZD7762 was also reported to increase bone remodeling, indicating that better CHEK1/2 inhibitors may be used to treat cancer and prevent bone loss during bone metastasis." (PMID 37862420, 2023). "More specifically, CHEK1 germline and somatic mutations have been observed in cancers such as breast, endometrial, colorectal and stomach, and germline mutations within ATR have been linked to an increased risk of developing oropharyngeal cancer and other malignancies." (PMID 36358700, 2022). "Interestingly, the prevalence of germline CHEK2 mutations in cancer patients outnumbers that in CHEK1 by the order of magnitude." (PMID 33322746, 2020). "Together with the fatal effects of its deficiency in mammals, it could be used to explain the paucity of cancer-associated alterations of CHEK1." (PMID 32178478, 2020). "Specifically, radiation therapy and chemotherapy induce DNA double-strand breaks as the main type of DNA damage whose repair is associated with PD-L1 upregulation in cancer cells through the activation of ATM/ATR/Checkpoint kinase 1 (Chk1) and STAT1/3–IRF1 pathway." (PMID 33114576, 2020).
cancer (continued). "CHEK1 showed association with family history of cancer (Pearson χ2 test, p = 0.02 *)." (PMID 31387239, 2019). "We hypothesize that these types of cancers will be susceptible to CHEK1 inhibition due to their poor ability to repair double strand DNA breaks." (PMID 25884494, 2015). "Our investigation not only demonstrated that miR-195 interacted with CHEK1 mRNA and suppressed its protein expression in cancer cells, but also showed that CHEK1 expression was associated with patient survival and the direction of the association was consistent with the action of miR-195." (PMID 25840419, 2015). "Indeed, our results confirm that the BRCA-mutated cell line PEO1 was the most sensitive of HGS cancers to treatment with TPT or CHEK1 inhibitor alone." (PMID 25884494, 2015). "Functionally, CHEK1 enhances cancer cell proliferation, migration, and cell cycle progression, which makes it a key driver of cancer progression and a potential therapeutic target." (PMID 41564103, 2026). "CRISPR screening reveals MIGs, especially CHEK1, as cancer-specific vulnerabilities, whose suppression impairs tumor proliferation and migration." (PMID 41722056, 2026). "CHEK1, a key effector kinase within the DNA damage checkpoint pathway, demonstrates significant differential expression across multiple cancer types." (PMID 41235705, 2025). "Prexasertib, a checkpoint kinase 1 (CHK1) inhibitor, has shown potential for cancers that exhibit high DNA replication stress and impaired DNA damage response pathways, such as HGSOC." (PMID 41029436, 2025). "Its role in cancer and other diseases has been widely studied, however, this is the first study to propose CHEK1 as a potential biomarker for AAD." (PMID 40561071, 2025). "Our analysis revealed that CHEK1 expression was consistently higher in tumor tissues compared to normal tissues across a range of cancer types, including BLCA, BRCA, COAD, and LIHC, with statistically significant differences (P < 0.001)." (PMID 40344565, 2025). "The potential anti-cancer effects of CHEK1 inhibitors are currently being evaluated in clinical trials as a single therapeutic agent or as potential enhancers of chemotherapeutic agents in combination." (PMID 40344565, 2025). "We propose the underlying mechanism that RBM17 promotes CHEK1 protein expression in the ATM/ATR pathway, triggering the development of chemoresistance in cancer cells." (PMID 40243905, 2025). "To elucidate the clinical significance of CHEK1 as a potent biomarker across various cancer types, we analyzed CHEK1 expression using RNA-seq data from 33 cancer types available through the UCSC Xena browser." (PMID 40344565, 2025). "Some kinases altered in SCLC and other cancers are Chk1 (checkpoint kinase 1), WEE1 (nuclear kinase), PARP (poly (ADP-ribose) polymerase), and AURK (Aurora kinase)." (PMID 38473324, 2024). "In our study, bioinformatics analysis revealed that CHEK1 was highly expressed in HCC and was closely associated with tumour biological properties, such as cancer cell invasion and migration, and EMT." (PMID 38842135, 2024). "The volcano plot of DEGs between 11 wart and 7 cancer samples of patients with EV shows differential expression of cancer-associated genes, such as FOS, JUND, PCNA, CHEK1, and CDKN2A." (PMID 36602881, 2023). "Increased CHEK1 expression has been reported in various cancers, including HNC, and was found to correlate with radioresistance and poor outcome, whereas CHEK1 inhibition has been demonstrated to have radiosensitizing effects." (PMID 37894339, 2023). "CHEK1/2 inhibitors have been shown to potentiate the effects of genotoxic chemotherapy drugs against cancer and some are being tested in clinical trials." (PMID 37862420, 2023). "For SAS cancer cells, arecoline leads to cell death, apoptosis, and cell cycle arrest by stimulating checkpoint kinase 1 (Chk1) and checkpoint kinase 2 (Chk2) phosphorylation." (PMID 38139811, 2023).
cancer (continued). "Regarding the mutation hotspots and mutation types in cancer, most of the truncating mutations of ATM, ATR, CHEK1, and CHEK2 are considered to be, at least, likely pathogenic." (PMID 37373360, 2023). "To probe therapeutic avenues, we show that the cancer-sensitizing agent and CHEK1/2 dual inhibitor AZD7762 can prevent radiation- and chemotherapy-induced primordial oocyte elimination." (PMID 37862420, 2023). "We used TIMER2.0 and CGGA for a comprehensive and systematic CDK1/PBK/CHEK1 oncogenic signature analysis for their differential expression in pan cancers and their correlation in GBM." (PMID 38003585, 2023). "Inhibitors targeting checkpoint kinases CHEK1/2 are being developed and tested as chemotherapy sensitizers, and they offer an attractive strategy to treat cancer and limit drug toxicity in ovaries." (PMID 37862420, 2023). "As such, combinatorial treatment strategies of Chek1/2 inhibitors with immune checkpoint inhibitors and radiation were evaluated in different cancers and were shown to have translational potential." (PMID 36949040, 2023). "An analysis of Cancer Cell Line Encyclopedia data showed that, like mPTCL, human T‐cell lymphoma lines tend to express higher levels of RPA2 (RPA32) and CHEK1 compared with all cancer cell lines overall." (PMID 35510955, 2022). "A published research has shown that CHEK1 is an important factor related to DNA replication and cell survival in cancer cells, and executes the function of the biological regulating enzyme in CCA." (PMID 35428780, 2022). "recently showed that cell cycle signaling was associated with high cancer stemness of EAC, such as E2F3, CHEK1, CDC20, SMC3, and TFDP1." (PMID 35785171, 2022). "The ataxia telangiectasia and rad3-related-checkpoint kinase 1 (ATR-CHK1) pathway is involved in DNA damage responses in many cancer cells." (PMID 35413091, 2022). "In some malignancies, CHEK1 upregulation was related to cancer progression, tumor recurrence, and resistance to treatment." (PMID 36313570, 2022). "Recent studies have revealed that CHEK1 is an oncogene in malignant tumor and plays an essential role in tumorigenesis, particularly in cancer prognosis and tumor phenotype." (PMID 35428780, 2022). "The cell cycle checkpoint proteins ataxia-telangiectasia-mutated- and Rad3-related kinase (ATR) and, its major downstream effector, checkpoint kinase 1 (CHK1) are activated in various cancer cells with damaged or incompletely replicated DNA." (PMID 34070674, 2021). "RFC2, CHEK1, PCNA, and POLE2 were also associated with worse overall survival in several types of cancer (Group A and D)." (PMID 34853396, 2021). "Taken together, inhibiting these genes from cluster 1 represents a promising therapeutic avenue in several types of cancer, especially focusing on the combined inhibition of CHEK1 and POLE2." (PMID 34853396, 2021). "LINC01224 can specifically upregulate the anti-apoptotic protein CHEK1 to influence the cancer cells." (PMID 34901153, 2021). "We also identified other deletions associated with higher HRD in multiple cancer types, such as XRCC2/3 and BARD1 deletion in BLCA, TP53BP1, and RAD51 deletion in OV and LUAD, and CHEK1 deletion in TCGT and SKCM, etc.." (PMID 34572800, 2021). "A growing number of studies have found that CHEK1 is highly expressed in multiple cancer species and is considered a potential target for cancer treatment." (PMID 34712733, 2021). "Our prior study reported that CHEK1 was included in the chromosomal instability gene list for cancer cells." (PMID 34090465, 2021). "CHEK1 is a major DNA repair checkpoint molecule and is involved in the pathogenesis of a variety of cancers, arguing for a role of failed DNA repair in these malignancies." (PMID 34281234, 2021).
cancer (continued). "To date, pharmacological inhibitors for Atr and Chek1 have already entered anti-cancer clinical trials either as stand-alone agents or combined with radio- or chemotherapy." (PMID 34158506, 2021). "By accessing TCGA data via cBioPortal, the mRNA levels of CHEK1 in various solid tumors were found to be differentially expressed in many cancer types." (PMID 32178478, 2020). "CHEK1 was also regulated at the post-transcriptional level by microRNAs which are key regulators of tumor growth and response to cancer treatment." (PMID 32178478, 2020). "Checkpoint kinase 1 (Chk1) expression is enhanced in most cancers owing to oncogenic activation and constant replicative stress." (PMID 33041328, 2020). "XL844 is a specific inhibitor of checkpoint kinase-1 and -2 and prevents the formation of a normal mitotic spindle; it can reportedly effectively sensitize cancer cells to induce cell cycle arrest." (PMID 32228488, 2020). "The majority of previous studies reported that CHEK1 expression is upregulated in various cancers, which is in agreement with this study." (PMID 32178478, 2020). "CHEK1 is majorly involved in the coordination of DNA repair and therefore is an area of great interest in cancer development and treatment." (PMID 32178478, 2020). "According to TCGA pan cancer studies, the most frequent genetic alterations of CHEK1 is deep deletion, which is most commonly found in testicular germ cell tumors (~8.7%) and uveal melanoma (5%)." (PMID 33224881, 2020). "Expression of proteins including CHEK1, CHEK2, ERCC1, ERCC2, PARP and WEE1 predispose cancer cells treated with chemotherapy toward DNA repair and proliferation." (PMID 35582583, 2019). "Many studies have reported that genetic variants in ATR/CHEK1 and ATM/CHEK2 are associated with cancer risk." (PMID 29928473, 2018). "A database analysis revealed upregulation of CDC6 mRNA expression in tumour compared to normal tissue and a correlation between CDC6 and CHEK1 mRNA expression in human cancers." (PMID 27775084, 2016). "During the last few years many Checkpoint kinase 1/2 (Chk1/Chk2) inhibitors have been developed for the treatment of different type of cancers." (PMID 27438145, 2016). "CHEK1 inhibitors are a novel approach to treatment, and have been used as single agents or in combination chemotherapy in many cancers." (PMID 25884494, 2015). "We are currently conducting a phase 2 clinical trial testing single agent CHEK1 inhibitor LY2606368 in women whose cancers are likely to have defects in DNA repair (NCT02203513)." (PMID 25884494, 2015). "This supposition is supported by the fact that (excluding hyper-mutated tumors) there are no occurrences of tumors with mutations in both RAD17 and either CHEK1, CHEK2 and WEE1 across all cancer types in TCGA." (PMID 26437225, 2015). "CDK2-cyclin E complex phosphorylates p57 at Thr310 of the QT-box domain; Akt, a kinase often deregulated in cancer, phosphorylates p57 at Thr310 or Ser282; while CHK1 (checkpoint kinase-1) phosphorylates p57 at Ser19." (PMID 26491224, 2015). "Additional evidence for this interaction was found in a large-scale functional shRNA screen of over 100 genotyped cancer cell lines, in which CHEK1/2 mutant cell lines were unexpectedly sensitive to RAD17 knockdown." (PMID 26437225, 2015).